TLR9 (toll like receptor 9)
Description:
Key component of innate and adaptive immunity. TLRs (Toll-like receptors) control host immune response against pathogens through recognition of molecular patterns specific to microorganisms. TLR9 is a nucleotide-sensing TLR which is activated by unmethylated cytidine-phosphate-guanosine (CpG) dinucleotides. Acts via MYD88 and TRAF6, leading to NF-kappa-B activation, cytokine secretion and the inflammatory response. Also acts via ADCY7, leading to cyclic di-AMP (c-di-AMP) synthesis and activation of the NLRP3 inflammasome (By similarity). Plays a role in defense against systemic mouse cytomegalovirus infection (By similarity). Controls lymphocyte response to Helicobacter infection (By similarity). Upon CpG stimulation, induces B-cell proliferation, activation, survival and antibody production.
Synonyms: CD289
Tractability: Small molecule: an approved drug acts on it; a high-quality ligand is known; it belongs to a druggable protein family. Antibody: its Gene Ontology location is reachable by antibodies, with high confidence; UniProt predicts a signal peptide or a membrane-spanning region. PROTAC: ubiquitination databases record sites on it; a small molecule that binds it is known. Other modalities: a drug acting on it is in phase 2 or 3 trials.
Target class: Toll-like and Il-1 receptors; Membrane receptor
Chemical probes: CHEMBL3357070
Gene: Protein-coding gene on chromosome 3 (52,221,080 to 52,225,645, reverse strand). Ensembl gene ENSG00000239732.
Subcellular location: Endoplasmic reticulum membrane; Early endosome membrane; Lysosome; Cytoplasmic vesicle, phagosome; Golgi apparatus membrane
Pathways (Reactome):
Immune System: MyD88 dependent cascade initiated on endosome; TRAF6 mediated IRF7 activation in TLR7/8 or 9 signaling; TRAF6 mediated induction of NFkB and MAP kinases upon TLR7/8 or 9 activation; Toll Like Receptor 9 (TLR9) Cascade; Trafficking and processing of endosomal TLR
Disease: Potential therapeutics for SARS
Signal Transduction: PI3K Cascade
Gene Ontology:
Molecular function: interleukin-1 receptor binding; pattern recognition receptor activity; siRNA binding; protein homodimerization activity; unmethylated CpG binding
Biological process: defense response to Gram-negative bacterium; detection of molecule of bacterial origin; negative regulation of ATPase-coupled calcium transmembrane transporter activity; positive regulation of B cell activation; positive regulation of B cell proliferation; positive regulation of canonical NF-kappaB signal transduction; positive regulation of chemokine production; positive regulation of gene expression; positive regulation of granulocyte macrophage colony-stimulating factor production; positive regulation of immunoglobulin production; positive regulation of inflammatory response; positive regulation of interferon-alpha production; positive regulation of interferon-beta production; positive regulation of interleukin-6 production; positive regulation of interleukin-8 production; positive regulation of JNK cascade; positive regulation of MAPK cascade; positive regulation of type II interferon production; regulation of B cell differentiation; toll-like receptor 9 signaling pathway; toll-like receptor signaling pathway; canonical NF-kappaB signal transduction; defense response to bacterium; defense response to virus; innate immune response; and 23 more
Cellular component: apical plasma membrane; basolateral plasma membrane; cytoplasm; early endosome membrane; endoplasmic reticulum; endoplasmic reticulum membrane; Golgi membrane; plasma membrane; early phagosome; endolysosome; endolysosome membrane; endosome; endosome membrane; extracellular region; lysosome; phagocytic vesicle
Genetic constraint (gnomAD): Loss-of-function variants: 22 observed, 28.15 expected, observed/expected ratio (o/e) 0.78, 90% interval 0.56 to 1.12. The upper end of that interval is the gene's LOEUF score, 1.12, which puts it in group 4 of 6, group 1 being the genes least tolerant of losing a copy. Missense variants: 1,065 observed, 1,383.3 expected, observed/expected ratio (o/e) 0.77, 90% interval 0.73 to 0.81. Synonymous variants: 579 observed, 615.95 expected, observed/expected ratio (o/e) 0.94, 90% interval 0.88 to 1.01.
Homologues: Orthologues: chimpanzee TLR9 (99% identical), macaque TLR9 (96% identical), dog TLR9 (82% identical), pig TLR9 (82% identical), guinea pig TLR9 (77% identical), rabbit TLR9 (75% identical), mouse Tlr9 (75% identical), rat Tlr9 (74% identical). Paralogues in human: SLIT1 (16% identical), SLIT2 (16% identical), SLIT3 (16% identical), SLITRK5 (15% identical), SLITRK3 (14% identical), LRRN2 (13% identical), SLITRK2 (13% identical), SLITRK4 (13% identical), SLITRK6 (13% identical), LRFN3 (13% identical), LINGO2 (13% identical), GP5 (12% identical), and 13 more.
Diseases named in the same sentence as TLR9 in open-access papers:
TLR9 is named in the same sentence as 537 diseases in open-access papers, as found by Europe PMC text mining. Sharing a sentence is not in itself a finding about the gene and the disease. The quoted sentences say what the papers report.
lupus (234 papers, 2008 to 2026). "These dual mechanisms—modulating lipid metabolism and dampening TLR9-driven inflammation—explain ART’s protective effects against lupus-associated atherosclerosis." (PMID 40867523, 2025). "To determine if differences between signaling downstream of TLR779 and TLR777 affect disease severity in vivo, we assessed lupus-associated phenotypes in Tlr7+/+ Tlr9–/–, Tlr779/779 Tlr9–/– MRL/lpr mice." (PMID 40794441, 2025). "For example, aberrant activation of TLR7 and TLR9 has been linked to the pathogenesis of systemic lupus erythematosus (SLE)." (PMID 41488647, 2025). "In vitro stimulation either with P. distasonis or via TLR9 allowed for the differentiation of IL-10 producing B cells which, in vivo, differentially accumulated in the Peyer ́s patches of Bank1-deficient lupus mice." (PMID 40761803, 2025). "The pathogenic role of TLR7 and the regulatory role of TLR9 in pDCs have been demonstrated in spontaneous murine models of lupus and PIL." (PMID 36853827, 2023). "Strikingly, studies show that Tlr9 deficiency in B cells in murine models of lupus is sufficient to accelerate renal disease even though deplete anti-nucleosome antibodies." (PMID 36875095, 2023). "It is known that pDCs potently produce type I IFNs in response to ligation of nucleic acid–sensing pattern recognition receptors (PRRs), such as TLR7 and TLR9, which have been implicated in lupus development." (PMID 36853827, 2023). "For example, the rs352140, rs187084 and rs5743836 polymorphisms of the TLR9 gene have been reported to be highly associated with a greater risk of developing systemic lupus erythematosus (SLE)." (PMID 37139337, 2023). "TLR7-deficient lupus mice show autoimmune inflammation remission, whereas TLR9-deficient lupus mice show a more severe autoimmune inflammation." (PMID 37872565, 2023). "That TLR9 deficiency reverses all of the phenotypes of Pld4thss/thss mice indicates that this strain is a rare murine lupus model that is mainly TLR9 driven." (PMID 37555846, 2023). "TLR7 and TLR9 single nucleotide polymorphisms (SNPs) have been linked to systemic lupus erythematosus in numerous studies (SLE)." (PMID 36439744, 2022). "In lupus-prone TLR9-deficient mice the enhanced lupus disease is associated with functionally upregulated expression of TLR7 by B cells and pDCs, whereas the disease is suppressed upon TLR7 deletion." (PMID 36389822, 2022). "The presence of spontaneous NETosis was described in lupus and has been linked to the presence of anti-DNA antibodies, chronic activation of pDCs via TLR9, and the induction of IFN-α secretion." (PMID 36389803, 2022). "Primary studies using different lupus-prone mouse strains crossed to TLR7- or TLR9-deficient mice, revealed that depletion of TLR7 ameliorates SLE, while surprisingly ablation of TLR9 exacerbates the disease." (PMID 36389822, 2022). "The presence of nucleic acids in the cytoplasm due to ineffective clearance activates endosomal TLR7 and TLR9; this is a major cause of systemic lupus erythematosus (SLE)." (PMID 34434197, 2021). "The lupus risk allele and regulator of TLR9 responses PLD4 was the most highly differentially expressed gene in IgMhi TS B cells." (PMID 33538776, 2021). "The TLR9 expression level was significantly increased in PTC ECs in lupus-prone AGN model mice and was associated with peritubular capillary and renal tubular interstitial injury." (PMID 33959133, 2021). "Toll-like receptor 7 (TLR7) and TLR9, which recognize single-stranded RNA and bacterial DNA, respectively, have been previously associated with lupus disease severity in mice." (PMID 32251357, 2020). "This is unexpected because the disease phenotype of other lupus-prone mouse strains is prevented by crossing to TLR7 KO mice, whereas crossing to TLR9 KO mice has actually been reported to exacerbate lupus by causing the up-regulation of TLR7." (PMID 31694920, 2019).
lupus (continued). "Several other polymorphisms in the TLR9 region like 1486C/T in the TLR9 promoter have been shown to be associated with diseases like lupus and rheumatoid arthritis." (PMID 30651082, 2019). "Exposure of phagocytes to apoptotic cell-associated DNA (a common antigenic source in experimental lupus), upregulated the expression of the transcription factor AhR (aryl hydrocarbon receptor) in a TLR9-dependent manner." (PMID 31354738, 2019). "ERα deficiency reduced the TLR9-dependent expression of PDC-TREM in pDCs from mice of NZM2410 (lupus-prone) or C57BL/6 genetic background." (PMID 28239379, 2017). "Overall, these results suggest that TLR2 and TLR9 are a new couple of pathogenic receptors involved in lupus progression that can be tested as therapeutic targets." (PMID 28410407, 2017). "Despite these several examples in which Tlr9 deficiency exacerbated lupus disease in monoallelic models, we are unaware of any other examples of Tlr9 deficiency in a spontaneous polygenic lupus model." (PMID 28278279, 2017). "The T allele of TLR9 gene polymorphism (rs5743836, −1237 C > T) was found to act as a risk factor of systemic lupus erythematosus (SLE) in South Indian Tamils." (PMID 28677621, 2017). "This is important because, though Tlr9 deficiency had been reported to accelerate disease in some other spontaneous lupus models, they were all driven by mutations in single alleles carried on the B6 background." (PMID 28278279, 2017). "In this respect, both TLR7 and TLR9 which initiate MYD88-dependent signalling pathways have been implicated in the pathogenesis of animal models of lupus and the production of anti-nuclear autoantibodies." (PMID 28456914, 2017). "The combination of the C allele at position -1486 with a G allele at position 1174 has the ability to downregulate TLR9 expression, and the C allele predisposes patients to systemic lupus erythematosus." (PMID 27105145, 2016). "Deficiency of Tlr7 leads to complete abrogation of lupus disease in some murine lupus models while deficiency of Tlr9 enhances its severity." (PMID 27228057, 2016). "Surprisingly, TLR9-deficient lupus mice have increased autoimmune disease; this is associated with greater production of anti-RNA autoantibodies." (PMID 26322049, 2015). "On the other hand, TLR9 deficient lupus-prone mice exhibited an exacerbation of the disease with increased serum levels of IgG and IFNα." (PMID 26110387, 2015). "Increased expression and activation of TLR7 and TLR9 has previously been implicated in autoimmune diseases such as systemic lupus erythematosus (SLE) in BXSB and other lupus prone Yaa mice, which have a Tlr7 duplication, and in humans." (PMID 25229618, 2014). "Initial results on the role of TLR9 in the MRL/lpr mouse were conflicting, but this appears to been resolved with the conclusion that there are less autoantibodies, but worse nephritis in TLR9 deficient lupus-prone mice." (PMID 24086313, 2013). "There are several studies on the association of TLR9 polymorphisms with systemic lupus erythematosus (SLE) in different ethnicities; however, the results are inconsistent." (PMID 22948541, 2013). "Stimulation of TLR9 in the endosomes by host DNA leads to plasmacytoid dendritic cell activation and type I interferon biosynthesis, which is implicated in lupus pathophysiology." (PMID 22948541, 2013). "TLR9 deficiency in some lupus models including MRLlpr/lpr mice can lead to reductions or alterations in antichromatin antibodies; however, TLR9 deficiency paradoxically leads to disease exacerbation in many experimental models." (PMID 21860649, 2012). "Another study demonstrated that the upregulation of TLR9 expression was associated with enhanced induction of HLA-DR in lupus B cells." (PMID 22952899, 2012). "To date, the TLR9 C2848T (rs352140) polymorphism has also been associated with Hodgkin’s lymphoma, periodontitis, ulcerative colitis, and systemic lupus erythematosus." (PMID 22714906, 2012).
lupus (continued). "In marked contrast, TLR9-deficient lupus-prone mice exhibit more severe lupus and activated pDC, which concords with our previous findings that TLR9 and CpG DNA is linked to protection from autoimmunity." (PMID 18997868, 2008). "Interestingly, although TLR9 promotes loss of tolerance to DNA in lupus, it is protective against systemic lupus erythematosus through MyD88-independent roles." (PMID 40924473, 2025). "However, a number of studies in a mouse model of lupus have shown that TLR7 plays a pathogenic role in the pathogenesis of lupus, while TLR9 plays a protective role in the pathogenesis of lupus." (PMID 38429401, 2024). "Although TLR7 and TLR9 co-express on pDCs and B cells and share downstream signaling pathways, whether TLR7 and TLR9 signaling have different roles in immune regulation in lupus’ pathogenic mechanisms is still under investigation." (PMID 36555668, 2022). "While the pathogenic role of nucleic acids in lupus is generally undisputed, further studies are needed to elucidate the relative contributions of and cross-regulation between the endosomal dsDNA/TLR9 pathway and the cytosolic DNA/STING pathway in individual patients." (PMID 35693769, 2022). "Because deleting TLR7 is not sufficient to rescue MRL/lpr or Tnip1-/- mice from nephritis, other TLRs such as TLR9 might also drive the increases in lupus-associated patrolling monocytes in these mice." (PMID 34868046, 2021). "On the other hand, biallelic loss-of-function mutations cause spondyloenchondrodysplasia with immune dysregulation (SPENCDI), a skeletal and neurological disorder with lupus-like symptoms and a type I interferon signature, in which TLR9 hyperactivation is suggested to cause immune dysregulation." (PMID 34868046, 2021). "Moreover, B cells express toll-like receptor 9 (TLR9), the receptor of CpG-DNA; and TLR9-deficient lupus mice exhibit exacerbated disease suggesting a protective role for TLR9 ligation in lupus." (PMID 33240280, 2020). "Thus, the disease accelerating effects of Tlr9 deficiency are separable from those mediated by the Fas mutation in the lupus-prone MRL genetic background." (PMID 28278279, 2017). "Tlr9 deficiency exacerbates autoimmune disease phenotypes on several lupus-prone backgrounds, though the exact mechanisms remain unclear and are likely to involve complex interactions among multiple cell lineages." (PMID 28278279, 2017). "In addition, bortezomib has been shown to suppress the trafficking of TLR9 to endolysosomes, inhibit TLR9 activation, and reduce lupus- and psoriasis-associated inflammation." (PMID 28894754, 2017). "However, deletion of TLR7 in Wiskott-Aldrich syndrome protein (WASp) in mice inhibited systemic autoimmunity, whereas deletion of TLR9 promoted systemic autoimmunity which recapitulates the phenotype seen in TLR7/9-deficient lupus mice." (PMID 28456914, 2017). "Furthermore, polymorphisms in TLR3, TLR7 and TLR9 genes have been associated with lupus patients in some populations and a number of in vivo and in vitro studies have strongly implicated a number of TLRs to play a role in the pathogenesis of lupus." (PMID 27846842, 2016). "A regulatory role for TLR signaling has also been reported in TLR9-deficient lupus-prone mice." (PMID 28018356, 2016). "Finally, both DNA-PKcs and TLR9 have been implicated in the development of autoimmune diseases such as lupus." (PMID 23533581, 2013). "Furthermore, TLR9 and MyD88 signaling have been linked to class switching to pathogenic IgG2a and 2b auto-antibodies in lupus." (PMID 19094215, 2008). "Variations in the TLR9 gene have been associated with several autoimmune disorders, but the relationship between TLR9 polymorphisms and systemic lupus erythematosus (SLE) remains controversial." (PMID 40821978, 2025). "Human self-DNA has been shown to activate TLR9 proteins in diseases such as systemic lupus erythematosus (SLE) and atherosclerosis, and mtDNA can cause inflammatory responses through TLR9 interactions." (PMID 39770994, 2024).